CD74 (CD74 molecule)
Diseases named in the same sentence as CD74 in open-access papers (continued):
Sharing a sentence is not in itself a finding about the gene and the disease.
spondyloarthritis (5 papers, 2018 to 2025). "Anti‐CD74 IgG and IgA antibodies were markedly increased in spondyloarthritis patients, displaying a high diagnostic value in axial spondyloarthritis and positive association with disease activity." (PMID 40761479, 2025). "CD74, also known as the MHC class II invariant chain, had been associated in patients with spondyloarthritis, back pain, and bladder pain indicating a shared immunological foundation underlying different forms of inflammatory pain." (PMID 40048323, 2025).
thyroid cancer (5 papers, 2014 to 2021). "Studies have shown that the overexpression of CD74 in thyroid cancer is associated with advanced tumour staging and can be used as a therapeutic target." (PMID 34957096, 2021). "A positive correlation between galectin-3 and CD74 expression was noted in thyroid cancer (unpublished observation)." (PMID 34035807, 2021). "Treatment of thyroid cancer cells with anti-CD74 antibodies inhibits cell growth, colony formation, cell migration and invasion, and secretion of vascular endothelial growth factors." (PMID 34957096, 2021). "We previously showed that treatment with anti-CD74 antibody inhibited cell invasion and vascular endothelial growth factor secretion in thyroid cancer cells." (PMID 34035807, 2021). "We have previously shown that inhibition of MIF/CD74 signalling axis blocks thyroid cancer cells growth by inducing cell death during mitosis." (PMID 28114961, 2017).
bladder cancer (4 papers, 2017 to 2024). "Similarly, CD74 overexpression is detected in high-grade invasive bladder cancer and is associated with proliferation, invasion, and angiogenesis of HT-1376 bladder cancer cells." (PMID 38732068, 2024). "Inhibition of MIF1/MIF2 reduces the tumor burden of bladder cancer in preclinical models, an effect that was found to be accomplished in part through activation of CD74, suggesting the significance of CD74 in tumor development." (PMID 38582956, 2024). "Another study revealed the mechanism of CD74 in the proliferation, invasion and angiogenesis of bladder cancer; indicating that it can be used as a potential therapeutic target for bladder cancer." (PMID 34957096, 2021).
Cirrhosis (4 papers, 2011 to 2025). A chronic disorder of the liver in which liver tissue becomes scarred and is partially replaced by regenerative nodules and fibrotic tissue resulting in loss of liver function. "The CD74, a protein of cirrhosis-HCC-risky related sub-network, is also membrane protein and the rest of the sub-network proteins are located extracellularly." (PMID 21526182, 2011). "Genes that are coordinately methylated in cirrhosis relative to normal liver, independent of etiology include CD74, which is highly expressed in the settings of inflammation and cancer." (PMID 25294808, 2014).
emphysema (4 papers, 2015 to 2022). "In addition, both MIF-deficient and CD74-deficient mice were found to develop aged-related emphysema and MIF-deficient mice developed even worse emphysema when exposed to cigarette smoke than MIF-deficient mice exposed to air." (PMID 35091838, 2022).
Hepatic steatosis (4 papers, 2019 to 2025). Steatosis is a term used to denote lipid accumulation within hepatocytes. "Additionally, diclofenac treatment caused hepatic steatosis, with some lipid vacuoles exhibiting positive CD74 staining." (PMID 40565363, 2025). "Mechanistically, MCT4 alleviated hepatic steatosis by regulating a group of hub genes such as Arg2, Olr1, Cd74, Mmp8, Irf7, Spp1, and Apoe, which in turn impacted multiple pathways involved in lipid metabolism and inflammatory response, such as PPAR, HIF-1, TNF, IL-17, PI3K-AKT, Wnt, and JAK-STAT." (PMID 40330148, 2025). "Additionally, Onecut1 and Cd74 were down-regulated in telmisartan-treated liver tissues but, in contrast to the present findings, these genes were inhibited during hepatic steatosis induction." (PMID 30850637, 2019).
HIV-1 infection (4 papers, 2014 to 2024). The type species of lentivirus and the etiologic agent of acquired immunodeficiency syndrome (AIDS). "However, the observed inhibition of HIV-1 infection upon the silencing of CD74 likely occurs due to the stopping of the CD74-mediated ERK/MAPK pathway." (PMID 38920978, 2024). "The authors hypothesize that CD74 plays a role in the early stages of HIV-1 infection by interacting with the gp41 loop region." (PMID 38920978, 2024). "Whether or not the ability of Nef to suppress MHC-II antigen presentation by up-regulation of CD74 may be modulated throughout the course of HIV-1 infection and if this Nef function plays a role in the pathogenesis of AIDS remains to be analyzed in larger patient cohorts." (PMID 24495362, 2014). "We have shown earlier that Vpu interacts with CD74 resulting in reduced surface expression of MHCII and attenuation of the immune response to HIV-1 infection." (PMID 24551192, 2014). "However, research on its contribution to HIV immune dysfunction has been limited even in face of the evidence of CD74 and MIF overexpression during HIV-1 infection." (PMID 36298774, 2022).
inflammatory bowel disease (4 papers, 2020 to 2024). A spectrum of small and large bowel inflammatory diseases of unknown etiology. "CD74 is involved in numerous inflammatory-related disease processes, and recent studies in inflammatory bowel disease (IBD) have shown a strong association between CD74 polymorphisms and the failure of anti-TNF therapy in patients with ulcerative colitis." (PMID 36445632, 2023). "Importantly, CD74 protein overexpression was detected in some malignant tumors, including cervical squamous cell carcinoma, urothelial bladder carcinoma, and in inflammatory bowel disease." (PMID 34572445, 2021). "Combined with CD74, MIF has been shown to promote wound healing in inflammatory bowel disease." (PMID 39974348, 2024). "Gene expression of cluster of differentiation 74 (CD74), the receptor for cytokine macrophage migration inhibitory factor, is increased in patients with inflammatory bowel disease (IBD), however, the role of CD74 signaling in intestinal inflammation remains poorly understood." (PMID 32004754, 2020).
ischemic stroke (4 papers, 2021 to 2026). A stroke disorder caused by obstruction of blood flow to the brain, due to thrombotic (local blood clot formation) or embolic (due to a blood clot or other material traveling from another site) event. "CD74, which plays multiple roles in immunity and inflammation, has been associated with intima-media thickness in subjects free from clinical cardiovascular diseases as well as with infarct size and neurological outcomes in subjects with ischemic stroke." (PMID 35050177, 2022). "By targeting CD74, we observed significant reductions in infarct size, inflammation, and long-term functional deficits, providing a strong rationale for further exploration of CD74 as a therapeutic target in ischemic stroke." (PMID 40400029, 2025). "This highlights the potential of CD74-targeted interventions in promoting both acute recovery following ischemic stroke." (PMID 40400029, 2025). "Previous studies have reported that Cd74 was highly expressed in M1 (inflammatory type) microglia in the hippocampal CA1 region following ischemic stroke with induced neuronal damage." (PMID 34881090, 2021). "However, the role of CD74 in ischemic stroke remains largely unexplored, underscoring the need for further research to clarify its mechanisms and therapeutic potential in this context." (PMID 40400029, 2025). "Our findings reveal a correlation between CD74 expression, microglial activation, pro-inflammatory cytokine production, and the exacerbation of ischemic injury, highlighting its importance in the pathophysiology of ischemic stroke." (PMID 40400029, 2025). "Increased CD74 expression contributes to inflammatory responses and ischemic stroke." (PMID 35050177, 2022). "Notably, CD74, a gene not previously studied in cerebral ischemia, was identified as a potential target for further investigation into its role and underlying mechanisms in ischemic stroke." (PMID 40400029, 2025).
kidney injury (4 papers, 2015 to 2024). Trauma to the kidney. "There is much less information on the expression of CD74 in acute kidney injury." (PMID 26441987, 2015).
lupus nephritis (4 papers, 2019 to 2023). Glomerulonephritis in the context of systemic lupus erythematosus. "However, elevated levels of CD74 and MIF positively correlated with worsening inflammation of lupus nephritis from the proinflammatory effects of MIF/CD74 signaling." (PMID 35626874, 2022).
mantle cell lymphoma (4 papers, 2018 to 2023). Mantle cell lymphoma is a rare form of malignant non-Hodgkin lymphoma affecting B lymphocytes in the lymph nodes in a region called the ``mantle zone''. "Furthermore, combinatory treatment approaches using anti-CD74 together with anti-CD20 antibodies resulted in enhanced induction of cell death as shown for mantle cell lymphoma (MCL) cells." (PMID 34638496, 2021). "In addition, FTY720 shows promising preclinical activity in mantle cell lymphoma (MCL) and sensitizes MCL cells to milatuzumab- (anti-CD74 humanized antibody-) mediated cell death." (PMID 29785244, 2018).
oral squamous cell carcinoma (4 papers, 2016 to 2026). "They reported the decreased infiltration of HLA‐DR+CD74+ neutrophils in oral squamous cell carcinoma (OSCC), which was consistent with our findings." (PMID 39447112, 2024). "Also, CD74-MIF/COPA/APP interactions were expressed in TME of oral squamous cell carcinoma after chemotherapy." (PMID 35784460, 2022).
proliferative diabetic retinopathy (4 papers, 2019 to 2025). Advanced retinopathy due to diabetes mellitus characterized by the formation of new vessels in the retina. "In the eye, increased levels of soluble CD74 and MIF have been detected in the vitreous and in endothelial and stromal cells in neovascular membranes of patients with proliferative diabetic retinopathy suggesting that MIF-CD74 signaling is implicated in disease progression." (PMID 33042148, 2020). "Another study reported the involvement of the MIF/CD74 signaling axis in proliferative diabetic retinopathy, suggesting that MIF expression is related to retinal neovascularization." (PMID 34445689, 2021). "We investigated the expression of MIF and its receptor CD74 in proliferative diabetic retinopathy (PDR) to reveal a possible role of this pathway in the pathogenesis of PDR." (PMID 31866994, 2019).
type 2 diabetes (4 papers, 2020 to 2025). "The pathways negatively associated with the genes coexpressed with CD74 were the lysine degradation pathway and the maturity-onset diabetes of the young pathway." (PMID 39118044, 2024). "It has been shown that both MIF and CD74 in serum and urine are dramatically elevated in patients with type 2 diabetes and are positively correlated with severe podocyte injury." (PMID 35563296, 2022). "Interestingly, the treatment of type 2 diabetes with metformin results in a significant fall in urinary MIF and CD74 excretion, suggesting that the anti-inflammation mechanism of metformin reduces podocyte injury and albuminuria by suppressing MIF-CD74-mediated renal inflammation." (PMID 35563296, 2022).
ulcerative colitis (4 papers, 2014 to 2024). An inflammatory bowel disease involving the mucosal surface of the large intestine and rectum. "We also found that rs4781011, which is associated to ulcerative colitis, is a trans-eQTL of CD74, a protein involved in immune response." (PMID 25010687, 2014). "In another study of the transition from ulcerative colitis to ulcerative colitis-associated colorectal cancer, the role of DPEP1, CD74, and CLCA1 in the progression of the disease was identified." (PMID 38339232, 2024). "Immunohistochemistry staining showed significantly higher expression of CD74 in colonic epithelial cells of IBD patients (Crohn's disease and ulcerative colitis) compared with healthy controls." (PMID 32004754, 2020).
uveal melanoma (4 papers, 2020 to 2024). A melanoma derived from melanocytes of the uveal tract. "APP-CD74 signaling has been previously implicated in uveal melanoma, where high expression of APP was identified in UM primary tumors compared to lower APP and higher CD74 expression in metastatic UM tumors." (PMID 38106024, 2023).
acute kidney injury (3 papers, 2020 to 2023). Sudden and sustained deterioration of the kidney function characterized by decreased glomerular filtration rate, increased serum creatinine or oliguria. "The specific role and mechanism pathways of MIF, its structural homologue MIF-2 and surface receptor CD74 in the progression of acute kidney injury needs to be investigated deeply, especially the related research of MIF-2 is still relatively few." (PMID 36117692, 2022). "Inhibition of MIF could also inactivate CD74-NF-κB signaling to protect kidneys against acute kidney injury." (PMID 38052787, 2023). "It was also possible that MIF may mediate acute kidney injury via CD74/TLR4-NF-κB signaling." (PMID 32964038, 2020).
acute myeloid leukemia (3 papers, 2015 to 2025). Acute myeloid leukemia (AML) is a group of neoplasms arising from precursor cells committed to the myeloid cell-line differentiation. "CD74 is aberrantly expressed in acute myeloid leukemia and is associated with aberrant activation of lymphocytes and the pathogenesis of Pre-T-ALL." (PMID 39422621, 2024).
astrocytomas (3 papers, 2023 to 2024). "Genes upregulated in astrocytomas include ID4, CD74 and FOS." (PMID 36865335, 2023).
brain tumors (3 papers, 2018 to 2023). "CD74 was expressed by tumor cells and by myeloid cells such as tumor associated microglia and macrophages (TAMs) as previously shown by our group in primary brain tumors." (PMID 29490700, 2018).
breast tumor (3 papers, 2017 to 2024). "In our study, we revealed that Cd68+ApoE+ cells were found in the TMEs of lung metastatic breast tumors were correlated with C1qa/b/c, Cd74, and ApoE expression." (PMID 39695088, 2024). "The CD74-ROS1 fusion gene combined an exon 7 of CD74 and an exon 34 of ROS1, and the ROS1 protein was overexpressed, driven by this fusion oncogene in breast tumor tissues." (PMID 34051833, 2021). "Use of a novel and validated colocalisation and image processing approach, coupled with co-immunoprecipitation, confirmed that CD74 and CD44 physically interact, suggesting a possible role in breast tumour growth." (PMID 29190904, 2017). "The level of CD44 in the breast tumor cell lines CAMA-1, MDA-MB-231, MDA-MB-435 and the immortalized normal luminal cell line 226LDM was higher than that of CD74." (PMID 29190904, 2017).
chronic obstructive pulmonary disease (3 papers, 2022 to 2025). A chronic and progressive lung disorder characterized by the loss of elasticity of the bronchial tree and the air sacs, destruction of the air sacs wall, thickening of the bronchial wall, and mucous accumulation in the bronchial tree. "CD74 also regulates cytosolic calcium homeostasis that plays a regulatory role in cardiac arrhythmias." (PMID 36712241, 2022).
crescentic glomerulonephritis (3 papers, 2015 to 2022). A histopathologic term for a pattern of diseases characterized by extensive crescent formation in the glomeruli; patients present clinically with rapid deterioration of renal function, and possible progression to end-stage renal failure within weeks or months. "MIF overexpression promotes while MIF targeting protects from experimental glomerular injury and kidney cysts, and interference with MIF/CD74 signaling or CD74 deficiency protected from crescentic glomerulonephritis." (PMID 26441987, 2015). "Further, it could interfere with MIF/CD74 signaling and CD74 deficiency, which can have protective effects against crescentic glomerulonephritis." (PMID 33779731, 2021). "However, genetic MIF/CD74 deficiency or blocking MIF activity can ameliorate glomerular injury and partially reverse established crescentic glomerulonephritis." (PMID 35360248, 2022). "Macrophage migration inhibitory factor (MIF), a pleiotropic, proinflammatory cytokine, produced by injured podocytes, is a signaling molecule that mediates pathological PEC proliferation via CD74/CD44, thereby leading to an aggressive and progressive course of crescentic glomerulonephritis." (PMID 35360248, 2022). "In addition to CD74, the signal transduction of MIF requires the recruitment and activation of CD44, a PEC activation marker, to induce PEC activation and pathological proliferation in crescentic glomerulonephritis." (PMID 35360248, 2022).
endometriosis (3 papers, 2014 to 2023). The growth of functional endometrial tissue in anatomic sites outside the uterine body. "With respect to experimental endometriosis induced using miR-451a deficient tissue, we were intrigued to find augmented expression of Cd74 compared to levels of expression in wild-type lesions." (PMID 35885004, 2022). "Mahdian and associates reported elevated MIF and CD74 mRNA expression in ectopic lesion tissue compared to eutopic endometrium from both control and patients with endometriosis, while we reported elevated CD74 protein expression and localization to glandular epithelium." (PMID 35885004, 2022). "Cd74 mRNA expression increased from 1 through 8 weeks post-endometriosis induction (week 0) but there was high variation among the fold increase in expression." (PMID 35885004, 2022). "The data obtained in this study provide further support for a role of Mif receptors, Cd74 and Cxcr4 in the pathophysiology of endometriosis." (PMID 35885004, 2022). "In summary, using a reproductively intact, immune competent mouse model of experimental endometriosis, we report lesion expression of Mif receptors Cd74 and Cxcr4." (PMID 35885004, 2022). "Using this model, we report for the first-time concurrent assessment of both Cd74 and Cxcr4 expression in endometriotic lesion tissue from mice with experimentally-induced endometriosis." (PMID 35885004, 2022). "In contrast to Cd74, Cxcr4 mRNA expression slightly increased at 1 week from induction (1.43-fold increase, p = 0.093) with minimal increase (p < 0.05) from weeks 2- and 4-weeks post-endometriosis induction (week 0) in mice with WT lesions." (PMID 35885004, 2022). "With respect to endometriosis, CXCR4 transcript and protein is expressed in human endometriotic lesion tissue including deep-infiltrating lesions, but its association with CD74 has not been assessed in experimental models for endometriosis." (PMID 35885004, 2022). "The action of MIF could be explained by the expression of its receptor, CD74, which was expressed in endometriosis-like lesions." (PMID 25329068, 2014). "CD74 expression analysis was performed for GSE7305 and GSE11691 in the endometriosis and normal groups, respectively." (PMID 37817158, 2023). "CXCR4 is capable of forming dimers with MIF-bound CD74; however, the majority of the studies which have evaluated CXCR4 in the context of endometriosis have been evaluating it as a receptor for CXCL12." (PMID 35885004, 2022). "In addition, we showed that endometriosis-like lesions and mouse endometrial tissue before inoculation (data not shown)were receptive to MIF because of the expression of its receptor CD74, as analyzed by immunohistochemistry." (PMID 25329068, 2014). "Cd74 is robustly expressed, and its expression increases with lesion growth and survival, expressing a similar pattern to that observed in humans as well as in a non-human primate model of experimental endometriosis." (PMID 35885004, 2022). "Similar to that observed in humans and a non-human primate model of endometriosis, Cd74 expression is elevated in lesion tissue in a temporal fashion while that of Cxcr4 shows minimal increase during initial lesion establishment but is reduced later during the lifespan." (PMID 35885004, 2022).